YTHDF2 (YTH N6-methyladenosine RNA binding protein F2)
Diseases named in the same sentence as YTHDF2 in open-access papers (continued):
Sharing a sentence is not in itself a finding about the gene and the disease.
cancer (continued). "YTHDF2 can recognize m6A-cotaining RNA and accelerate the degradation process to regulate many biological processes, such as viral infection, stem cell development and cancer progression." (PMID 37012388, 2023). "YTHDF2 also regulates the stability of lncRNAs and mRNA during cancer development." (PMID 36816363, 2023). "SUMOylation of YTHDF2 significantly enhances its binding affinity of m6A-modified mRNAs and subsequently contributes to deregulated gene expressions which bear responsibility for cancer progression." (PMID 39872957, 2023). "YTHDF2 can stabilize MYC mRNA of cancer stem cells and it might be a potential target to regulate MYC signaling pathway in glioblastoma." (PMID 37598390, 2023). "This suggested that YTHDF2 inhibition is an effective approach to enhancing cancer immunotherapy." (PMID 38022518, 2023). "Since YTHDF2 plays an important role in cancer progression and O-GlcNAcylation could enhance its protein stability, we wondered whether O-GlcNAcylation of YTHDF2 is involved in HCC progression." (PMID 36765030, 2023). "YTHDF2, as an important reading protein, is significantly downregulated in liver cancer cells and leads to severe inflammation, vascular reconstruction, and cancer metastasis." (PMID 36578520, 2022). "Taken together, these findings highlight the complicated roles of m6A regulators in macrophages and suggest that METTL3/14 and YTHDF2 may be potential targets for cancer immunotherapy." (PMID 35296338, 2022). "Furthermore, YTHDF1 and YTHDF2 impacted cancer via binding m6A sites in the 3′-UTR of EGFR transcription and contributed to aberrant activities of downstream signal pathways." (PMID 36517820, 2022). "YTHDF2 primarily relies on m6A modification to modulate signaling pathways in cancer cells." (PMID 35382893, 2022). "Hence, we explored the association between the expression of YTHDF2 and ICP genes in human cancers to explore the potential role of YTHDF2 in immunotherapy." (PMID 36120577, 2022). "We employed KM plot to explore the prognostic value of YTHDF2 expression in human cancer." (PMID 35661004, 2022). "The positive pan-cancer correlations with m1A RNA methylation regulatory proteins YTHDF2 and ALKBH1, m5C methylation regulatory proteins DNMT1, DNMT3B, and ALYREF, and m6C RNA methylation regulatory proteins HNRNPC, HNRNPA2B1, and ELAVL1 were particularly significant." (PMID 36090896, 2022). "However, when NR4A1 was reintroduced into the cells, the aggressive cancer progression promoted by overexpressed YTHDF2 was substantially hindered." (PMID 36566195, 2022). "Similarly, ACC, UCEC, and TGCT are the top three cancers with significant correlation between YTHDF2 expression and estimate scores." (PMID 36120577, 2022). "YTHDF2 can destabilize key gene transcripts and inhibit cancer cell proliferation." (PMID 35480327, 2022). "Dysregulation of YTHDF2 in cancer could also regulate EMT, glucose metabolism, and apoptosis, which have been considered as significant factors in the progression of cancer." (PMID 35382893, 2022). "Results suggested that YTHDF2 was elevated in different cancer cell lines." (PMID 35661004, 2022). "We evaluated m-6-A modified protein, which showed IMPDH1 was closely related to m-6-A related regulatory proteins in pan-cancer, and we focused on evaluating the association of IMPDH1 with the top four proteins: YTHDF1, ALKBH5, YTHDF2, METTL3 in HCC, indicating a strong relationship." (PMID 36618420, 2022). "The following GO functional annotation and KEGG pathway analysis in various cancers indicated that YTHDF2 could positively regulate cell adhesion, cell cycle, and immune-related functions." (PMID 36120577, 2022). "Moreover, we also investigated that YTHDF2 expression was correlated with its CNVs and promoter methylation in most cancer types." (PMID 36120577, 2022). "mRNA decay of tumor suppressor genes in cancer progression is mainly mediated by YTHDF2." (PMID 35094011, 2022).
cancer (continued). "However, the development and therapeutic effects of YTHDF2-related products still need to be further explored in the direction of cancer treatment." (PMID 35382893, 2022). "Mounting evidence has reported that YTHDF2 plays a significant role in the cancer progression." (PMID 35661004, 2022). "Accumulating data suggest that YTHDF2, a reader protein responsible for m6A-mediated mRNA decay, is closely related to many aspects of human cancers by regulating multiple biological processes, such as metastasis, proliferation, differentiation and inflammation." (PMID 35986274, 2022). "The biological significance of YTHDF2 was conducted in different cancers." (PMID 36120577, 2022). "We also investigated the role of YTHDF2 on immune infiltration levels across cancers." (PMID 36120577, 2022). "The diverse functions of YTHDF2 may depend on the different contexts of cancers or by modulating different target genes." (PMID 35382893, 2022). "However, it should be noted that YTHDF2 was found to play opposite roles in different types of cancers as well." (PMID 35924072, 2022). "Previous findings suggest that YTHDF1 or YTHDF2 may be a therapeutic target for cancer immunotherapy or a predictive biomarker predicting the response to anti-PD-1/PD-L1." (PMID 36479088, 2022). "Recent studies indicated that YTHDF2 regulated AKT pathway in cancers." (PMID 36566195, 2022). "YT521-B homology domain family 2 (YTHDF2) has been identified as a member of m6A reader protein involving in many vital biological processes, whereas its role and functional mechanisms in cancers remain unclear." (PMID 36120577, 2022). "Furthermore, YTHDF2 was a high-risk factor in LIHC, LGG, ACC, SARC, and KICH, while a low-risk gene in other cancer types, particularly in READ." (PMID 36120577, 2022). "Still, the reverse effect of YTHDF2 in distinct cancers or even in identical cancer might be related to genes with contrary functions or distinct binding sites, and the specific mechanism remains to be further elucidated." (PMID 35382893, 2022). "However, further researches are still needed to expound the specific role of YTHDF2 in human cancers and non-cancers." (PMID 33593354, 2021). "However, the relevant reasons why YTHDF2 played opposite roles in different cancers were still unclear." (PMID 33593354, 2021). "In addition, we also found that IGF2BP3 and YTHDF2 were regulated by eight different DMPs across six cancers." (PMID 33718187, 2021). "YTHDF2 takes a great part in multiple biological processes, such as migration, invasion, metastasis, proliferation, apoptosis, cell cycle, cell viability, cell adhesion, differentiation and inflammation, in both human cancers and non-cancers." (PMID 33593354, 2021). "YTHDF2, a “reader” of RNA m6A modification, is involved in cancer progression." (PMID 34970571, 2021). "YTHDF2 supports the cancer stem cell phenotype and metastasis in patients with liver cancer." (PMID 34512342, 2021). "Indeed, we have discovered many other candidate targets of YTHDF2, which are also involved in cancer growth and metastasis." (PMID 33980824, 2021). "The TIMER2 method was used to examine the expression status of YTHDF2 across TCGA cancer forms." (PMID 34512342, 2021). "It was also declared that YTHDF2 was dysregulated in human non-cancers." (PMID 33593354, 2021). "In prostate cancer, YTHDF2 can promote cancer cell migration." (PMID 33552994, 2020). "However, YTHDF2 promotes the cancer stem cell liver phenotype and cancer metastasis by binding m6A-modified OCT4 mRNA." (PMID 33015074, 2020). "In addition, GSEA showed that YTHDF2 impacted on multiple cancer signaling pathways, including mTOR pathway, GSK3 pathway, EIF4 pathway, and CHREBP2 pathway." (PMID 33102202, 2020). "Researchers demonstrated that YTHDF2 played key roles in the cancer progression." (PMID 33102202, 2020).
cancer (continued). "Therefore, elucidation of how YTHDF2 is regulated and its proteolysis pathway would potentially benefit the development of new therapeutic strategies to manipulate YTHDF2 levels in cancers—such as AML —or for ex vivo amplification of hematopoietic stem cells." (PMID 32267835, 2020). "In addition, YTHDF2 expression upregulated in the other cancers, with a fold change from 2.038 to 11.69." (PMID 32986017, 2020). "Although YTHDF2 is a well-known m6A reader in several cancers." (PMID 32814762, 2020). "Therefore, we investigated the correlation of YTHDF2 expression with immune infiltration levels in 32 cancer types from the TIMER database." (PMID 32986017, 2020). "Recently the regulatory role of YTHDF2 involved in human cancers also loomed up." (PMID 33121495, 2020). "Removal of IL11 abrogated the growth competitiveness of YTHDF2-deficient SMMC7721 cells, while a SERPINE2 deficit attenuated the proangiogenic capacity of SMMC7721 cells, highlighting that IL11 and SERPINE2 are key targets of YTHDF2 in cancer-promoting inflammation." (PMID 31735169, 2019). "In YTHDF2-deficient cells, re-expression of wild-type YTHDF2 but not the catalytically inactive mutant offset the acquired cancer-promoting inflammatory phenotypes, and reduced both phosphorylation of STAT3 and stabilization of IL11 and SERPINE2 mRNAs." (PMID 31735169, 2019). "Indeed, HIF-2α-mediated inhibition of YTHDF2 in HCC cells provides proof of concept that hypoxia adapts cancer epigenetics for aggressiveness, which is due, at least in part, to the stabilization of m6A-containing oncogene mRNAs." (PMID 31735169, 2019). "However, YTHDF2 may contribute to the cancer stem cell phenotype through the YTHDF2/OCT4 pathway, and at the same time, it could act as an HCC suppressor, influencing the ERK/MAPK pathway and initiating EGFR mRNA decay." (PMID 41157107, 2025). "Accumulating evidence suggests that the YT521-B homologydomain family 2 (YTHDF2), one of the m6A “readers,”is associated with various biological processes in cancers and noncancerousdisorders, impacting migration, invasion, metastasis, proliferation,apoptosis, and cell cycle." (PMID 40017738, 2025). "However, there are few reports of small molecule compounds targeting YTHDF2 for cancer therapy." (PMID 40756353, 2025). "Moreover, except for PD‐L1 and VEGFA, our study found that YTHDF2 modulates many crucial genes involved in cancer‐associated signaling pathways (data not shown), implying critical role of YTHDF2 in HCC progression and calling for further researches." (PMID 38247171, 2024). "Importantly, YTHDF2 was found to be a promising prognostic biomarker in different cancers." (PMID 38075202, 2024). "MiR-145 and miR-495 could directly target YTHDF2 to affect the development of malignant tumors." (PMID 35382893, 2022). "In summary, YTHDF2 could act as a target of miRNA to participate in the progression of cancer." (PMID 35382893, 2022). "Moreover, we employ the CCLE databases to examine YTHDF2 expression in various cancer cells lines." (PMID 35661004, 2022). "Finally, we detected the promoter methylation level of YTHDF2 across cancers using UALCAN database." (PMID 36120577, 2022). "Therefore, YTHDF2 might have a far-reaching influence on the development of human diseases, especially cancers." (PMID 33593354, 2021). "Therefore, YTHDF2 may exert different effects on different cancers by targeting mRNA transcripts of different genes, and further elucidation of the role of YTHDF2 and its new targets in the development of LUAD is needed." (PMID 33980824, 2021). "In addition, the expression of YTHDF2 is also increased in many different cancers, suggesting that YTHDF2 might be an important oncogene." (PMID 33980824, 2021). "Moreover, emerging researches indicate that YTHDF2 predicts the prognosis of different cancers." (PMID 33593354, 2021). "Moreover, YTHDF2 is related to cancer stem cells (CSCs) in AML." (PMID 32986017, 2020).
cancer (continued). "Furthermore, multivariate Cox regression model revealed that YTHDF2 (HR = 0.471, 95% CI: 0.241–0.920; P = 0.028) as well as age (HR = 2.118, 95% CI: 1.142–3.931; P = 0.017) and cancer status (HR = 3.329, 95% CI: 1.608–6.526; P = 0.001) served as independent prognostic factors (P < 0.05)." (PMID 33102202, 2020). "In addition, YTHDF2 expression was associated with CD8+ T cell levels in 12 cancer types, CD4+T cell levels in 14 cancer types, macrophage levels in 14 cancer types, neutrophil levels in 12 cancer types, and DC levels in 12 cancer types." (PMID 32986017, 2020). "Nonetheless, a deficit in YTHDF2 expression may shift m6A-editing into a cancer-specific mode." (PMID 31735169, 2019). "The data suggested that YTHDF2 binds with m6A methylated GATA3 mRNA and recruits Dis3L2 to induce its degradation in cancer cells." (PMID 39800682, 2025). "For instance, YTHDF2 modulates the m6A methylation of OCT4 mRNA to promote the cancer stem cell phenotype and cancer metastasis; while METTL3 promotes HCC progression through an m6A-YTHDF2-dependent post-transcriptional silencing of SOCS2." (PMID 39799112, 2025). "The MIDN level was correlated with several immune checkpoint genes, such as VEGFA, and RNA modification genes such as YTHDF1, YTHDF2, YTHDF3, and YTHDC1 in cancers." (PMID 40002690, 2025). "Positive correlations between the expression of YTHDF3, YTHDF2, YTHDF1, and YTHDC1 and MIDN levels were detected in nearly all cancers." (PMID 40002690, 2025). "In cancer tissues, both YTHDF1 (p < 0.05) and YTHDF2 (p < 0.001) show significant upregulation compared to para‐cancerous tissues, with YTHDF1 exhibiting a more pronounced increase in fold changes (Log2FC = 1.31 vs. 0.98)." (PMID 38683130, 2024). "Depletion of YTHDF2 activates the EMT-specific pathway in BC cells, particularly in TNBC, leading to further activation of cancer-related translation initiation factors." (PMID 39054967, 2024). "In cancer cells, m6A writer complex (METTL3/METTL14/WTAP)‐mediated modification of c‐Myc mRNA is protected from YTHDF2‐mediated degradation by MSI2 with c‐Myc overexpression." (PMID 39661414, 2024). "YTHDF2 mediated the degradation of FENDRR and promoted cancer cell proliferation by increasing SOX4 expression in EEC." (PMID 37478120, 2023). "In detail, m6A sites are highly enriched on LncRNA THOR transcripts and specific m6A readers YTHDF1 and YTHDF2 can read the m6A motifs and regulate the stability of the LncRNA THOR, thus mediating the proliferation, migration and invasion of cancer cells." (PMID 37365581, 2023). "Functionally, the knockdown of STUB1 promoted cell proliferation, while the knockdown or inhibition of HSP90β significantly limited cancer progression in HCC, similar to the knockdown of YTHDF2." (PMID 37515378, 2023). "YTHDF2 degrades m6A-containing IL-11 and SERPINE2 mRNAs, two mediators of hypoxia-induced cancer cell survival and vascular reconstruction." (PMID 37369946, 2023). "Among the 68 HCC patient specimens that underwent immunohistochemical staining, all cancer tissues were positive for METTL14, YTHDF2, and ZC3H13 staining in contrast to the adjacent tissues." (PMID 36936652, 2023). "Compared with the normal tissues, except for the lower YTHDF2 expression in KIRP tissues and similar YTHDF2 expression in KICH, KIRC and LAML tissues, YTHDF2 was overexpressed in all the left 23 cancer types." (PMID 36120577, 2022). "M6A readers (YTHDF2, IGF2BP2, etc.)can work synergistically with m6A writers and erasers during the oncogenesis of various cancers." (PMID 35804965, 2022). "And we performed knockdown experiments for YTHDF2 and HNRNPA2B1 to reveal the biological role in the cancer cell invasion and metastasis." (PMID 35847857, 2022).
cancer (continued). "YTHDF2, a member of the m6A reader proteins containing the YT521-B homology (YTH) domain family, has been reported to play important roles in cancer progression." (PMID 35661004, 2022). "It has been found that YTHDF2 can regulate m6A methylation of OCT4 mRNA to promote liver phenotype and cancer metastasis in cancer stem cells." (PMID 35487915, 2022). "For example, it has been shown that YTHDF2 promotes the CSC liver phenotype and cancer metastasis by modulating the m6A methylation of OCT4 mRNA." (PMID 35309512, 2022). "Knockdown experiment results revealed that m6A regulators, YTHDF2 and HNRNPA2B1 participated in the cancer cell invasion and metastasis." (PMID 35847857, 2022). "An increasing number of studies have confirmed that m6A writers (METTL3, METTL14, KIAA1429, WTAP), erasers (FTO and ALKBH5) and readers (YTHDC1, YTHDC2, YTHDF1, YTHDF2 and HNRNPC) have distinct functions within different types of cancer cells." (PMID 35042525, 2022). "The other three YTH family proteins, YTHDF3, YTHDC1, and YTHDC2, were found to be less correlated with human cancer than YTHDF1 and YTHDF2." (PMID 33795663, 2021). "However, the relationship between YTHDF2 and cancer is largely unknown." (PMID 32111180, 2020). "It is possible that alteration of YTHDF2 expression impacted on 6-PGD and cancer metabolic-related pathways in human ccRCC." (PMID 33102202, 2020). "YTHDF1, along with YTHDF2 and YTHDF3, redundantly suppresses the IFN‐γ response by destabilizing IRF1 mRNA, suggesting that these proteins can serve as viable therapeutic targets in cancer immunotherapy." (PMID 39587835, 2025). "YTHDF2 and YBX2 have the capacity to collaborate on heat shock protein family A (Hsp70) member 6 (HSPA6) mRNA to regulate HSPA6 expression by modulating its stability, which regulates the survival and progression of cancer cells." (PMID 39904996, 2025). "METTL3 May posttranscriptionally upregulate the levels of inhibitor of DNA binding 2 (ID2) in an m6A/YTHDF2-dependent mechanism, thereby enhancing ID2 mRNA stability and promoting cancer cell proliferative capacity." (PMID 40986143, 2025). "Mechanistic studies dissecting the low-complexity domains and condensate behavior argue for nonidentical roles of YTHDF1 and YTHDF2, while cancer models continue to implicate IGF2BPs in stabilizing drug-resistance transcripts (e.g., ABCB1)." (PMID 41280938, 2025). "In numerous cancers, there is a consistent observation of dysregulated expression of key enzymes involved in m6A modification, including "writers" (such as METTL3, METTL14, WTAP), "erasers" (like FTO, ALKBH5), and "readers" (including YTHDF1, YTHDF2, YTHDF3)." (PMID 38270643, 2024). "Similarly, FENDRR is an onco-suppressor lncRNA which is regulated by YTHDF2 in endometrioid endometrial carcinoma (EEC) and is involved in cancer cell proliferation inhibition." (PMID 38075202, 2024). "Additionally, YTHDF2 increases the m6A levels in the 5’UTR of OCT4 mRNA in tandem with promoting OCT4 expression, eventually accelerating the HCC cancer stem cell (CSC) phenotype and metastasis." (PMID 36999016, 2023). "Furthermore, knockdown of YTHDF2 in cancer cells was shown to attenuate the upregulation of PVT1 and reversed the half-life of PVT1, indicating that YTHDF2 was vital to the stability of PVT1 and affected the progression of tumors." (PMID 35382893, 2022). "The correlation between YTHDF2 expression and 47 ICP genes were verified in most cancer types." (PMID 36120577, 2022). "For example, loss of the lncRNA, THOR, inhibits the proliferation, migration, and invasion of cancer cells in vitro and in vivo, while the m6A readers, YTHDF1 and YTHDF2, can regulate THOR, thereby inhibiting the occurrence and development of tumors in vivo and in vitro." (PMID 35692827, 2022). "Downregulation of YTHDF2 increased the expression of SOCS2 and negatively regulated the JAK/STAT signaling pathway, which suppressed the phosphorylation of STAT5 and inhibited the growth of cancer cells." (PMID 35382893, 2022).